INS (insulin)
Diseases named in the same sentence as INS in open-access papers (continued):
Sharing a sentence is not in itself a finding about the gene and the disease.
breast cancer (continued). "Not much is known about the mechanism, by which insulin treatment would possibly influence the receptor phenotype of breast cancer." (PMID 28076434, 2017). "Over 20% of the MCF-7 breast cancer cells underwent apoptosis when treated with compound A or B. The addition of insulin did not result in significant changes in the ratio of apoptotic cells." (PMID 29371977, 2017). "Thus, the IR–DDR1 crosstalk constitutes a positive feedback loop enhancing the effects of insulin and IGF-2 in breast cancer cells." (PMID 28591735, 2017). "We next evaluated whether DDR1 expression could modulate the biological effects of insulin and IGF-2 in breast cancer cells." (PMID 28591735, 2017). "When the amount of insulin bound to the receptor reaches a particular threshold, the stimulatory effects of human insulin on breast cancer cells no longer increase." (PMID 28427228, 2017). "In a panel of breast cancer cells, DDR1 knockdown by specific siRNAs markedly inhibited IR downstream signaling as well as proliferation, migration and colony formation in response to insulin and IGF-2." (PMID 28591735, 2017). "Now, by using siRNA strategy, we have demonstrated not only that Sam68 is mediating both insulin and leptin stimulated cellular metabolism, but also its participation in the leptin and insulin dependent activation of MAPK and PI3K signalling pathways in breast cancer cells." (PMID 27415018, 2016). "The insulin, IGF, GH and LEP pathways are well-characterized in the biological literature, and previous literature suggests important functions or potential functions for each of these genes in breast cancer." (PMID 27942580, 2016). "Reduction in serum insulin levels was also observed in non-diabetic breast cancer patients with metformin treatment." (PMID 27430256, 2016). "Fourth, we studied the link between insulin use and breast cancer mortality rather than its incidence." (PMID 26171401, 2015). "There were 59,798 ever-users and 422,235 never-users of human insulin, with respective numbers of incident breast cancer of 559 (0.93 %) and 4,711 (1.12 %), and respective incidence of 207.9 and 215.1 per 100,000 person-years." (PMID 26537234, 2015). "For those who died of breast cancer and those who did not, the median duration of followup was 3.7 and 7.4 years, respectively, and the median duration of insulin use in insulin users in the 2 groups was 6.0 and 4.0 years, respectively." (PMID 26171401, 2015). "IL-6 signaling pathways occur early in the inflammatory cascade with subsequent downstream effects on insulin-signaling molecules and insulin pathways (e.g., IGF-1), which may be related to weight gain, recurrence, and survival of patient with breast cancer." (PMID 25793000, 2015). "Fasting insulin levels were not different between women with and without breast cancer (standardized mean difference, SMD −0.03, 95%CI −0.32 to 0.27; p = 0.9)." (PMID 24911052, 2014). "Other ligands to which breast cancer cells commonly respond include FGFs, IGF/INS, and HGF." (PMID 24655548, 2014). "The insulin and insulin-like growth factor receptor (IGFR) - mediated molecular pathways have recently emerged as important effectors of neoplastic transformation and proliferation in various malignancies, including breast cancer." (PMID 24637962, 2014). "It has been reported that metformin reduces circulating insulin levels and improves insulin sensitivity in non-diabetic women with early-stage breast cancer." (PMID 24887156, 2014). "The fasting insulin levels (11 studies, n = 14,372) were not different between women with and without breast cancer (SMD −0.03, 95% CI −0.32 to 0.27, P = 0.9)." (PMID 24911052, 2014). "More direct evidence from in vitro cell line studies indicated that IGF-1, insulin and estradiol induced the expression of leptin and OBR mRNA in the MCF-7 breast cancer cell line, while in MDA-MB-231 cells, leptin and OBR mRNA expression was induced by insulin or hypoxia." (PMID 23425972, 2013).
breast cancer (continued). "Interestingly, 61% of women operated for breast cancer (cases) with HOMA-IR ≥ 2.5 presented fasting plasma glucose levels and fasting plasma insulin levels in the normal range (group 1)." (PMID 23497533, 2013). "The effect of insulin on recurrence and survival is being addressed in the recent NCIC Clinical Trials Group MA.32, which is a phase III randomized trial of metformin versus placebo in early stage breast cancer patients." (PMID 23050155, 2012). "In vitro, glargine stimulates the growth of breast cancer cells to a greater extent than human insulin in most, but not all, cell lines." (PMID 23209929, 2012). "In our experiments, increased glucose and insulin caused an up-regulation of PLCγ in SW480 colon cancer cells, but no up-regulation in MDA-MB-468 breast cancer cells." (PMID 22554284, 2012). "In a cohort of over 500 women without known diabetes followed prospectively, fasting insulin levels correlated with distant recurrence and death after breast cancer treatment." (PMID 23050155, 2012). "In stratified analyses by study design, the odds of breast cancer was not elevated with insulin glargine use compared to non-glargine insulin use in observational studies (OR 1.02, 95% CI 0.68 to 1.53, P = 0.92; p for heterogeneity = 0.000, I2 = 83%)." (PMID 23284776, 2012). "One mechanism involves a stimulatory effect of insulin on the growth rate of the breast cancer that are present not yet of a size that can be diagnosed." (PMID 23284776, 2012). "We examined mRNA from a panel of breast cancer cell lines by real-time RT-PCR and found that compared to MCF10A, PHGDH was expressed at higher levels in the majority, including SUM44 cells, which required insulin for proliferation." (PMID 21437235, 2011). "While not all breast cancer cells demonstrate the insulin-independent phenotype, 7 of 9 breast cancer cell lines we examined did." (PMID 21437235, 2011). "We did not add any insulin to the medium in primary culture to maintain the cell lines, while it was necessary for most of routinely used breast cancer cell lines, such as MCF-7, T-47D, MDA-MB-435S and so on." (PMID 19121212, 2009). "The right pane focuses on biochemical assay and genotyping for breast cancer (BC) and control groups, featuring pie charts for genotyping of CD295 and ITLN1, highlighted tests like insulin and leptin, and a comet assay with red fluorescent images." (PMID 41221514, 2025). "Interestingly, it has been shown that breast cancer (BC) cells inhibit pyruvate kinase (PKM) in pancreatic islet β-cells by secreting miR-122-rich extracellular vesicles, which in turn reduces insulin secretion and leads to dysregulation of glucose homeostasis." (PMID 40881702, 2025). "Research has shown that the binding of insulin and IGF‐1 to the insulin receptor can activate the PI3K/AKT/mTORC signaling pathway, stimulating cell proliferation and the transcription of metabolic genes, which promotes the growth of cancer cells and prevents apoptosis in breast cancer cells." (PMID 40550558, 2025). "Moreover, PA increases insulin sensitivity by reducing Insulin Growth Factor 1 (IGF-1) and inflammation, which may help to protect against breast cancer." (PMID 36980159, 2023). "Other biomarkers like insulin, C-C motif chemokine ligand 2 (CCL2), transforming growth factor β 1(TGF-β1), and Treg-like molecule (Treg: Regulatory T cells) were also discussed in some of our reviewed publications, regarding their relevance primarily to breast cancer treatment." (PMID 37181043, 2023). "In addition, BRCA has also been described as a metabolic regulator through its complex interactions with insulin/IGF-1 signaling axis and as transcriptional repressor of the gene IGF1R, main key players in the pathogenesis of T2DM-related complications and in breast cancer onset and progression." (PMID 37510134, 2023).
breast cancer (continued). "Preclinical evidence demonstrated that ketogenic diet was able to reduce spikes in serum insulin and glucose and suppress downstream PI3K/mTOR signaling in PI3Ki-treated mice better than metformin, and also improve response to PI3Ki in multiple tumor types including breast cancer." (PMID 35016012, 2022). "Studies of osteoblasts, breast cancer cells, endothelial cells, and of particular relevance, brown adipocytes have shown that genetic reduction of IGF-1 R expression enhances insulin sensitivity, indicating that the insulin-generated signal is negatively regulated by an interaction with the IGF-1 R." (PMID 35734881, 2022). "Moreover, high insulin levels also reduce the production of SHBG synthesized by the liver and increase the proportion of circulating estradiol, leading to the growth of breast cancer." (PMID 33842335, 2021). "The goal was to examine metformin impact on metabolic factors in non-diabetic subjects and determine whether this impact varies by baseline BMI, insulin, and rs11212617 SNP in CCTG MA.32, a double-blind placebo-controlled randomized adjuvant breast cancer (BC) trial." (PMID 34103538, 2021). "Increase in survival due to metformin and metformin-analogues has also been reported in transgenic ErbB2/neu mice, implying that add-on insulin sensitizers may improve survival of non-diabetic ErbB2 breast cancer." (PMID 32695336, 2020). "Findings from this study suggest that among breast cancer survivors with a generally healthy BMI, neurotrophic factors, inflammation, or insulin pathways may not be the mechanisms for changes in cognition in a physical activity intervention." (PMID 31605514, 2019). "If weight loss can be achieved, breast cancer survivors have the potential to improve insulin-related parameters, which may decrease chances of negative breast cancer outcomes." (PMID 29587682, 2018). "Finally, in non-diabetic woman with breast cancer, a study showed that metformin decreased circulating insulin levels by 22% and increased insulin sensitivity by 25%." (PMID 30186236, 2018). "However, a large European study found no overall increase in breast cancer for type two diabetic patients, irrespective of type of treatment: sulfonylurea (hazard ratio (HR): 0.98), metformin (HR: 0.90), or insulin (HR: 1.07)." (PMID 27832382, 2017). "As IRS-1 and IRS-2 are thought to mediate most of the effects of IR and IGF-1R in breast cancer cells, it may be possible to disrupt this molecule without affecting normal glucose homeostasis mediated by other adapter proteins in insulin target organs." (PMID 29152592, 2017). "Our recent reports indicate that pharmacological aryl hydrocarbon receptor (AHR) ligands inhibit breast cancer cell responses to IGFs, suggesting that targeting AHR may have benefit in cancers whose proliferation and survival are dependent on insulin/IGF signaling." (PMID 25699021, 2015). "The in2c transcript is insulin-regulated in prostate and breast cancer cell lines (data not shown)." (PMID 25376984, 2014). "The few studies that have examined the effects of exercise training on particular components of MetS in postmenopausal breast cancer survivors have shown reduced insulin levels and waist circumference, but no change in insulin resistance, fasting glucose, or body weight." (PMID 24708832, 2014). "We do not have information on family history of breast cancer, parity, or measures of other hormones such as insulin or leptin that might influence endogenous sex hormone concentrations." (PMID 23113944, 2012). "Insulin stimulation increased MMP-9 levels, demonstrating that insulin may also enhance cell signaling pathways which lead to metastasis from the site of primary tumors in breast cancer." (PMID 22226054, 2012).
breast cancer (continued). "To characterize the effects of CR (with and without IGF-1 infusion) in the microenvironment in which mammary tumors arise in mice, we ran Insulin-PCR Super arrays (SABiosciences, Frederick, MD) using mRNA extracted from the mammary fat pads of control, 30% CR, and 30% CR + IGF-1 mice." (PMID 23342276, 2012). "More recently, insulin and IGF-1 have been demonstrated to induce the expression of the zinc transporter LIV-1 in ER positive breast cancer cells and the regulation of this zinc transporter may be important for invasiveness and estrogen-independent cell growth." (PMID 22852056, 2012). "In the current study, we focus on one phenotype that can be observed in vitro, which distinguishes transformed and cancer cells from nontransformed cells, i.e., the insulin-independent proliferation of oncogene-transformed breast epithelial cells and breast cancer cells in serum-free media." (PMID 21437235, 2011). "Importantly, there is considerable evidence that IR-A, which has the peculiar characteristic to bind not only insulin but also IGF-2, may play a critical role in the development of breast cancer, thyroid cancer and leiomyosarcoma." (PMID 20209060, 2010). "Therefore, 11 insulin-responsive cell lines were screened for insulin-induced EphA2 regulation, including four hepatoma (HepG2 WT, HepG2 IGF1R KO, Hep3B, and H4IIE), three acute myeloid leukemia (AML) (MOLM-13, THP1, and EOL-1), and four breast cancer cell lines (BT549, BT474, HCC38, and HCC1937)." (PMID 39572596, 2024). "However, the role of vanadium in targeting breast cancer stem cells has yet not been explored, but there are many insulin mimetic vanadium compounds in clinical trials that could have the potential of successfully treating breast cancer and cancer stem cells." (PMID 35159385, 2022). "In addition to increased tumor growth, the presence of elevated endogenous insulin levels and IR signaling have also been postulated to encourage metastasis through the promotion of EMT in both human and mouse tumor models in the context of breast cancer and prostate cancer." (PMID 33604295, 2020). "In this study, we find that the Insulin/IGF1R signaling pathway is activated in 78 of 90 (~ 87%) of patients with invasive breast cancer and in 45 of 51 (~ 88.2%) TNBC patients, suggesting IGF may be a promising therapeutic target for this highly aggressive breast cancer subtype." (PMID 29367764, 2018). "Since it has been reported that estradiol increases FASN expression in breast cancer cells and that insulin increases FASN expression in liver, we examined whether fatty acids could also decrease the estradiol- or insulin-induced increase in FASN expression in MCF-7 breast cancer cells." (PMID 29282029, 2017). "Given the known roles of estradiol, insulin, and IGFs in breast cancer etiology as well as the role of zinc in the regulation of aromatase and protooncogenes, LIV-1, may play a critical role in maintaining zinc homeostasis and therefore be vital to the development and progression of breast cancer." (PMID 22852056, 2012). "Similarly, in estrogen responsive breast cancer cell lines, growth response to insulin could be specifically inhibited by anti-IR but not anti-IGF-IR blocking antibodies while it can be mimicked by an anti-IR stimulating antibody." (PMID 22927847, 2012). "In addition, metformin reduced circulating insulin levels by 22% and improved insulin sensitivity by 25% in non-diabetic women with breast cancer, highlighting the insulin-lowering effects of metformin as a potential mechanism of action in the treatment of breast cancer." (PMID 21470407, 2011). "Despite the lack of further mTOR activation following chronic insulin stimulus, our findings indicate that both MCF-7 and MDA-MB-231 breast cancer cell lines exhibit a constitutively active mTOR pathway at baseline, a feature that is documented by other works." (PMID 40806650, 2025).
breast cancer (continued). "In women with newly diagnosed breast cancer without diabetes, adding metformin to adjuvant therapy has been shown to decrease IGF-1, ratio of IGF-1 to IGFBP-3, insulin, fasting blood glucose, and HOMA-IR." (PMID 38543182, 2024). "We exposed each breast cancer cell to 10μM TAM in both LG and HG growth medium supplemented or not by insulin for 48 hrs." (PMID 37361518, 2023). "Although metformin has been introduced as a new drug for several types of cancer in recent years, our meta-analysis results show that metformin therapy is not able to influence insulin, FBS, HOMA-IR, and BMI levels in endometrial and breast cancer patients." (PMID 33917520, 2021). "Statins similarly failed to inhibit HDAC activity in MDA-MB-231 breast carcinoma cells and BRIN-BD11 insulin-secreting cells, while sodium butyrate and TSA showed significant inhibition (p < 0.0001)." (PMID 30974899, 2019). "These mutant mice are obese and insulin-resistant, but their progeny produced by crossing with mammary tumor-prone mice (MMTV-TGF-α) showed no mammary tumors despite of their body weights were significantly heavier than those from lean groups." (PMID 24202338, 2013). "However, in breast cancer cells, IRS4 can induce constitutive PI3K/AKT hyperactivation even in the absence of insulin or growth factors." (PMID 39227585, 2024). "Present systematic findings indicate that metformin could decrease insulin levels, FBS, BMI, Ki-67, and HOMA-IR in non-diabetic patients with endometrial and breast cancer in some studies." (PMID 33917520, 2021). "Physical activity in breast cancer survivors may be more effective at modifying serum IGF-1 levels in women who are not taking tamoxifen, on the insulin pathway may be more pronounced for obese or sedentary women." (PMID 33467265, 2020). "Since some changes as induced by IGFBP5 downregulation could be mimicked by insulin, some by CoCl2 and others neither by insulin nor CoCl2, it is likely that IGFBP5 fulfills several different functions in breast cancer cells." (PMID 26515727, 2015). "Second, although we compared insulin, C-peptide levels and HOMA-IR scores univariably between women with and without breast cancer, we also meta-analyzed risks measures of breast cancer between quartiles that were adjusted at least for age, and in most of cases for several essential confounders." (PMID 24911052, 2014). "Also, insulin and IGF1 are able to stimulate ER transcriptional activity in breast cancer cells, even in the absence of estrogen." (PMID 23750285, 2013). "Protein expression was determined by western blot analysis in MDA-MB-468 breast cancer and SW480 colon cancer cells previously cultured under physiologic (5.5 mM) and diabetogenic (11 mM) glucose concentrations (without and with 100 ng/ml insulin)." (PMID 22554284, 2012). "As breast tumors often express higher levels of the IGF-1 receptor, it is of no surprise that insulin and IFG-1 have been correlated with early recurrence and decreased relapse-free survival in breast cancer as well as increased resistance of tumor cells to both chemotherapy and radiation therapy." (PMID 23050155, 2012). "According to these results, the insulin-induced phosphorylation of DDR1 has been described in cancer cells, and the constitutive phosphorylation of DDR1 is present in several oral squamous cell carcinoma cells but not in other cell types, such as breast cancer T24D cells." (PMID 36675255, 2023). "GPER, which is considered as a negative prognostic marker in breast cancer, has been shown previously to be upregulated and/or activated by a plethora of stimuli classically involved in HIF-1 pathway, including hypoxia, EGF, IGF1, insulin and the metals copper and zinc." (PMID 29212519, 2017).
breast cancer (continued). "In a window of opportunity trial of metformin in non-diabetic breast cancer patients, Dowling and colleagues examined both the direct actions of the drug on cancer cells (as mediated by AMP kinase), as well as its indirect actions (as mediated by circulating insulin)." (PMID 26111812, 2015). "However, it should be noted that the growth medium DFCI-1 used for the normal human mammary epithelial cells contains additional growth factors that are not presented in the medium for maintaining the breast cancer cells, which include EGF, estradiol, and insulin." (PMID 22494620, 2012).